Vault (Vault RNA )
Gene: Miscellaneous RNA gene on chromosome 2 (206,007,880 to 206,007,974, reverse strand). Ensembl gene ENSG00000252485.
Homologues: Orthologues: chimpanzee Vault (100% identical), macaque Vault (97% identical), tropical clawed frog Vault (62% identical), tropical clawed frog Vault (61% identical), mouse Vaultrc5 (60% identical), tropical clawed frog Vault (60% identical), mouse Vaultrc-ps1 (59% identical), tropical clawed frog Vault (59% identical), tropical clawed frog Vault (57% identical), rat Vault (55% identical). Paralogues in human: VTRNA2-2P (74% identical), Vault (73% identical), VTRNA1-1 (55% identical), VTRNA1-2 (55% identical), VTRNA1-3 (55% identical), Vault (55% identical), VTRNA3-1P (52% identical).